STIP1 (stress induced phosphoprotein 1)
Description:
Acts as a co-chaperone for HSP90AA1. Mediates the association of the molecular chaperones HSPA8/HSC70 and HSP90 (By similarity).
Synonyms: STI1; Hop; HEL-S-94n; IEF-SSP-3521; P60; STI1L
Tractability: Small molecule: a structure with a bound ligand is known. Antibody: the Human Protein Atlas places it where antibodies can reach. PROTAC: UniProt records ubiquitination sites on it; ubiquitination databases record sites on it; its protein half-life has been measured.
Gene: Protein-coding gene on chromosome 11 (64,185,272 to 64,204,548, forward strand). Ensembl gene ENSG00000168439.
Subcellular location: Cytoplasm; Nucleus; Dynein axonemal particle
Subcellular location (Human Protein Atlas): Cytosol; Plasma membrane; Nucleoplasm
Pathways (Reactome):
Cellular responses to stimuli: HSP90 chaperone cycle for steroid hormone receptors (SHR) in the presence of ligand
Signal Transduction: RND1 GTPase cycle
Gene Ontology:
Molecular function: Hsp90 protein binding; protein binding; RNA binding
Cellular component: protein folding chaperone complex; protein-containing complex; cytoplasm; cytosol; dynein axonemal particle; Golgi apparatus; nucleus
Genetic constraint (gnomAD): Loss-of-function variants: 16 observed, 79.61 expected, observed/expected ratio (o/e) 0.2, 90% interval 0.14 to 0.31. The upper end of that interval is the gene's LOEUF score, 0.31, which puts it in group 1 of 6, group 1 being the genes least tolerant of losing a copy. Missense variants: 524 observed, 715.93 expected, observed/expected ratio (o/e) 0.73, 90% interval 0.68 to 0.79. Synonymous variants: 258 observed, 258.89 expected, observed/expected ratio (o/e) 1, 90% interval 0.9 to 1.11.
Homologues: Orthologues: chimpanzee STIP1 (100% identical), macaque STIP1 (99% identical), dog STIP1 (97% identical), guinea pig STIP1 (97% identical), mouse Stip1 (97% identical), pig STIP1 (97% identical), rat Stip1 (96% identical), rabbit STIP1 (96% identical), tropical clawed frog stip1 (88% identical), zebrafish stip1 (80% identical). Paralogues in human: SPAG1 (19% identical), RPAP3 (18% identical), UNC45A (16% identical), UNC45B (16% identical), TOMM34 (15% identical), TTC12 (14% identical), ST13 (12% identical), TOMM70 (11% identical), DNAAF4 (11% identical), TTC4 (10% identical), STUB1 (10% identical), TTC1 (10% identical), and 6 more.
Diseases named in the same sentence as STIP1 in open-access papers:
STIP1 is named in the same sentence as 96 diseases in open-access papers, as found by Europe PMC text mining. Sharing a sentence is not in itself a finding about the gene and the disease. The quoted sentences say what the papers report.
ovarian carcinoma (15 papers, 2013 to 2025). A malignant neoplasm originating from the surface ovarian epithelium. "Taken together, these results indicate that high STIP1 histoscores are associated with a particularly aggressive behavior in ovarian cancer." (PMID 23468915, 2013). "Conversely, targeted downregulation of endogenous STIP1 expression resulted in a decreased proliferation of pancreatic cancer, ovarian cancer, and osteosarcoma cells." (PMID 35269562, 2022). "Ovarian cancer tissues have also been reported to secrete STIP1, enabling the use of STIP1 levels as a prognostic disease biomarker." (PMID 35626686, 2022). "In this regard, increased STIP1 serum levels in patients with ovarian cancer and hepatocellular carcinoma have been shown to activate the ERK2, SMAD1/5, and PI3K-AKT signaling pathways." (PMID 35269562, 2022). "Significant increases in the expression of STIP1 have been reported in several solid tumors, including hepatocellular carcinoma, pancreatic cancer, ovarian cancer, colon cancer, breast cancer, and cholangiocellular carcinoma." (PMID 35269562, 2022). "A recent study showed that autoantibodies against STIP1 were significantly elevated in the serum levels of patients with ovarian cancer, compared with the normal controls." (PMID 28852266, 2017). "In cancers, STIP1 can be translocated to cell surface or secreted out of the cell by ovarian cancer and glioblastoma cells, and stimulates cancer cell proliferation in an autocrine manner." (PMID 28199984, 2017). "One report showed that STIP1 induced ovarian cancer cell proliferation through binding with the activin A receptor, type II-like kinase 2 (ALK2)." (PMID 28199984, 2017). "Several malignancies including hepatocellular carcinoma, pancreatic cancer, ovarian cancer, colon cancer, and cholangiocellular carcinoma are characterized by STIP1 overexpression." (PMID 27409672, 2016). "PLA performed in formalin-fixed paraffin-embedded ovarian cancer tissues clearly demonstrated the interactions between STIP1 and STAT3, STIP1 and JAK2, as well as STIP1 and HSP90 localized mainly in cytoplasm." (PMID 27409672, 2016). "STIP1 has recently been shown to be secreted by human ovarian cancer cells and is well-known as a biomarker of ovarian carcinoma." (PMID 25010044, 2014). "Although the release of STIP1 from human ovarian cancer has been confirmed by an independent research group, few data are available on the usefulness of STIP1 immunohistochemical analysis for assessing prognosis in ovarian cancer." (PMID 23468915, 2013). "For the identical anti-STIP1 antibody used in IHC throughout this study, western blot analysis of multiple ovarian cancer cell lines also confirmed its specificity in recognizing STIP1." (PMID 23468915, 2013). "The expression of StIP1 is obviously downregulated in paclitaxel-resisted ovarian cancer cell strain OC3/Tax300." (PMID 24455688, 2013). "Stress-induced phosphoprotein 1 (STIP1) has been recently identified as a released biomarker in human ovarian cancer." (PMID 23468915, 2013). "We further investigated the clinical significance of STIP1 immunoexpression in ovarian cancers according to their histological type and grade." (PMID 23468915, 2013). "By comparing the proteomes of the tumor interstitial fluid (TIF) and the normal interstitial fluid (NIF), we have recently identified stress-induced phosphoprotein 1 (STIP1) as a candidate biomarker for human ovarian cancer." (PMID 23468915, 2013). "We have previously reported that STIP1 is secreted by ovarian cancer cells in the tumor microenvironment and the systemic circulation." (PMID 23468915, 2013). "The treatment of ovarian cancer cells with recombinant STIP1 stimulated cell proliferation and migration, but co-treatment with anti-STIP1 antibodies abrogated this effect." (PMID 23468915, 2013). "Serum STIP1 levels are significantly higher in patients with ovarian cancer than in age-matched healthy controls and decrease significantly after surgical removal of the tumor." (PMID 23468915, 2013).
ovarian carcinoma (continued). "We have also described the molecular mechanisms by which secreted STIP1 stimulates the proliferation of ovarian cancer cells." (PMID 23468915, 2013). "In this study, a total of 330 ovarian cancer tumor samples were evaluated for STIP1 expression by immunohistochemistry and analyzed for a possible correlation with patient characteristics and survival." (PMID 23468915, 2013). "The effective blockade of rhSTIP1-stimulated cell proliferation and migration of ovarian cells elicited by anti-STIP1 antibodies indicates that secreted STIP1 from cancer tissues can be a target for the development of therapeutic antibodies in ovarian cancer." (PMID 23468915, 2013). "In patients with grade 3 ovarian cancer, patients with STIP1>169 (n = 102) had a significantly (P = 0.022) worse 5-year survival rate of 44.5% than 63.6% in those with STIP1≤169 (n = 11)." (PMID 23468915, 2013). "Taken together, these findings suggest that STIP1 secreted by human ovarian cancer cells promotes cancer cell proliferation by acting in an autocrine and/or paracrine fashion." (PMID 23468915, 2013). "Stress-induced phosphoprotein 1 (STIP1) is secreted by ovarian cancer cells." (PMID 35693928, 2022). "Interestingly, clinical studies demonstrated that an increased STIP1 protein expression portends adverse outcomes in ovarian cancer." (PMID 27409672, 2016). "In addition, the combined measurement of CA125 and STIP1 has been shown to improve the early detection of ovarian cancer, supporting the clinical usefulness of STIP1 as a biomarker in this malignancy." (PMID 23468915, 2013). "In ovarian cancer cells treated with rhSTIP1, siRNA knockdown of STIP1, or anti-STIP1 antibodies, we also used MTT assays to evaluate cell viability as a proxy for the cell number, with the understanding that cell number is shaped by the forces of both cell proliferation and apoptosis." (PMID 23468915, 2013). "If corroborated by other studies, our data suggest that STIP1 may serve as a promising target for antibody-based ovarian cancer therapy." (PMID 23468915, 2013). "In addition, STIP1 secreted by human ovarian cancer cells has been shown to promote tumor cell proliferation by binding to ALK2 (activin A receptor, type II-like kinase 2) and activating the SMAD-ID3 signaling pathways." (PMID 23468915, 2013). "In ovarian cancer, we have shown that STIP1 binds to a bone morphogenetic protein (BMP) receptor – termed activin A receptor, type II-like kinase 2 (ALK2) – to activate the SMAD signaling pathway and the transcriptional activation of ID3 (inhibitor of DNA binding 3)." (PMID 23468915, 2013). "In this study, we have shown that the STIP1 histoscores may be useful in supplementing the pathologist’s histopathological grading of ovarian cancers by providing objective, quantitative assessments." (PMID 23468915, 2013). "Clinicopathological characteristics and STIP1 histoscorea in 330 patients with ovarian cancer." (PMID 23468915, 2013). "In our previous studies, we have demonstrated that STIP1 is secreted by ovarian cancers in the bloodstream, suggesting that this molecule may serve as a released biomarker of ovarian cancer." (PMID 23468915, 2013). "This study shows for the first time that STIP1 is a prognostic biomarker in human ovarian cancer." (PMID 23468915, 2013). "To investigate the potential usefulness of STIP1 immunohistochemical expression as a biomarker in ovarian cancer, we used the ROC curve to quantify how well different histoscores could be used for the prediction of survival." (PMID 23468915, 2013). "Moreover, the treatment with rhSTIP1 resulted in an increased Ki-67 immunostaining, suggesting that STIP1 induces human ovarian cancer cell proliferation." (PMID 23468915, 2013). "Our findings suggest that STIP1 expression may be related to prognosis and that the STIP1 pathway may represent a novel therapeutic target for human ovarian cancer." (PMID 23468915, 2013).
ovarian carcinoma (continued). "We have previously shown that STIP1 maintains JAK2 protein stability and prevents apoptosis in ovarian cancer." (PMID 35269562, 2022). "On analyzing human ovarian cancer specimens, JAK2 and STIP1 expression levels were found to be positively correlated with each other." (PMID 35269562, 2022). "Wang and colleagues found that stress-induced phosphoprotein 1 (STIP1), a protein adaptor and modulator of heat shock proteins HSP70 and HSP90, was secreted by ovarian cancer cells and found in the blood of ovarian cancer patients." (PMID 31683698, 2019). "Ovarian cancer tissues were subjected to immunohistochemistry (IHC) and PLA to investigate the in vivo interactions between STIP1 and JAK2." (PMID 27409672, 2016). "To investigate the biological functions of STIP1, we treated BG1 and MDAH2774 ovarian cancer cells with rhSTIP1 (400 nM)." (PMID 23468915, 2013). "STIP1 was identified to be overexpressed in several kinds of cancers, such as colorectal carcinoma (CRC), pancreatic cancer, cholangiocellular carcinoma (CCC), ovarian cancer, and so on." (PMID 28852266, 2017). "In contrast to the neutralizing effect of anti-STIP1 on the rhSTIP1-stimulated cell proliferation, direct treatment of ovarian cancer cells with various clones of anti-STIP1 did not change the MTT readings." (PMID 23468915, 2013). "Serum STIP1 levels were not shown to significantly differ among patients with 4 clinical stages of ovarian cancer, but in this study tumor STIP1 histoscores were significantly higher in stages III–IV (n = 147) than stages I–II (n = 183)." (PMID 23468915, 2013). "We also performed an analysis of deviance and constructed the time-dependent ROC curves (either with or without STIP1) to examine whether the addition of STIP1 histoscores could improve the prognostic stratification of patients with invasive ovarian cancers." (PMID 23468915, 2013). "Because borderline ovarian tumors are generally characterized by a good prognosis and are not commonly included in ovarian cancer clinical trials, the independent prognostic significance of STIP1 levels was analyzed only in the subgroup of patients with invasive ovarian cancer (n = 280)." (PMID 23468915, 2013).
glioma (14 papers, 2009 to 2023). A benign or malignant brain and spinal cord tumor that arises from glial cells (astrocytes, oligodendrocytes, ependymal cells). "For example, STIP1 knockdown also inhibited proliferation and motility of colorectal, breast, lung, glioma, and gastric cancer cell lines, emphasizing that high expression of STIP1 is linked to cancer progression." (PMID 36713524, 2022). "STIP1 is secreted by and shown to induce proliferation in glioma tumour cells through MAPK and P13 pathways." (PMID 19216797, 2009). "Strikingly, increased levels of STIP1 are also noted in microglia/macrophages as glioma progresses." (PMID 36555253, 2022). "Furthermore, a significant upregulation of STIP1 expression is observed in glioma-infiltrating macrophages." (PMID 36555253, 2022). "The downregulation of STIP1 increases cell apoptosis of glioma cells." (PMID 34671271, 2021). "STIP1 is overexpressed at both mRNA and protein levels in OSCC samples compared with normal tissues, similar as, for example, in gliomas, colorectal cancers, hepatocellular carcinoma, gastric cancers, cervical carcinomas, lung cancers, pancreatic cancers and breast cancers." (PMID 36713524, 2022). "In addition, stress-induced phosphoprotein 1 (STIP1) secreted by TAMs induces proliferation of glioma cells in vitro, while IL-10 was shown to promote glioma cell proliferation via JAK2/STAT3 signaling in a glioma model." (PMID 34503065, 2021).
gastric cancer (8 papers, 2013 to 2024). A primary or metastatic malignant neoplasm involving the stomach. "In mouse metastatic models with STIP1 silenced in gastric cancer cells and in hepatocellular carcinoma cells, metastatic lung nodules were inhibited." (PMID 36713524, 2022). "It is possible that STIP1 regulates the Wnt/β-catenin pathway by indirectly affecting the activity of p-GSK-3β in gastric cancer." (PMID 29335007, 2018). "USP43 promotes gastric cancer progression by stabilizing STIP1 through deubiquitination." (PMID 39605891, 2024). "In the present study, we investigated the role of STIP1 on metastasis of gastric cancer (GC)." (PMID 29335007, 2018).
glioblastoma (8 papers, 2017 to 2023). The most malignant astrocytic tumor (WHO grade IV). "STIP1 also modulates proliferation of astrocytes and retinal cells, and is associated with glioblastoma." (PMID 28820892, 2017). "Recombinant STIP1, as well as microglial-secreted STIP1, has been demonstrated to promote cell migration of glioblastoma cells." (PMID 32365744, 2020).
pancreatic cancer (8 papers, 2009 to 2024). "A recent study reported the association of STIP1 with tumour invasion in pancreatic cancer using RNAi silencing, highlighting STIP1 as a potential cancer gene." (PMID 23737949, 2013). "When GOLPH3 and STIP1 are knocked down, they can not only inhibit the proliferation of pancreatic cancer cells, but also inhibit the expression of cyclin D1 in cancer cell." (PMID 38594465, 2024). "High levels of STIP1 have been detected in a number of malignancies, including hepatocellular carcinoma, ovarian cancer, colon cancer, and pancreatic cancer." (PMID 29914167, 2018). "In pancreatic cancer, Stip1 knockdown reduces tumor invasiveness via matrix metalloproteinase-2 downregulation." (PMID 29914167, 2018). "In summary, knockdown of STIP1 and VIM by siRNA resulted in decreased invasion and proliferation (STIP1) in the highly invasive pancreatic cancer cell line, Clone #3." (PMID 19216797, 2009). "STIP1 can promote the proliferation of pancreatic cancer cells and accelerate the cell cycle." (PMID 38594465, 2024). "The knockdown of STIP1 has been shown to suppress the invasiveness of pancreatic cancer cells." (PMID 23468915, 2013). "For example, stress-induced phosphoprotein 1 (STIP1), an adaptor protein that coordinates the assembly of heat shock proteins, has been reported to be over-expressed in colon and pancreatic cancers." (PMID 23737949, 2013). "Three novel proteins, ALDH1A1, STIP1 and VIM were chosen to validate and further investigate their involvement in pancreatic cancer invasion." (PMID 19216797, 2009). "Elevated expression of STIP1 was observed in pancreatic tumour tissue compared to normal pancreas, whereas ALDH1A1 stained at lower levels in pancreatic tumours, as detected by immunohistochemistry." (PMID 19216797, 2009). "Expression of STIP1 and ALDH1A1 in pancreatic tissue was investigated using IHC analysis of pancreatic tumour and normal tissue." (PMID 19216797, 2009). "This study also showed that the overexpression of GOLPH3 was positively correlated with the expression of STIP1 in pancreatic cancer tissue, but the knockout of GOLPH3 did not affect the level of STIP1." (PMID 38594465, 2024). "STIP1 expression, through survival pathways and MMP activation, could contribute to invasion in the highly invasive Clone #3 pancreatic cancer cell line, therefore making it a potentially valuable target for pancreatic cancer therapy." (PMID 19216797, 2009).
hepatocellular carcinoma (7 papers, 2016 to 2024). A malignant tumor that arises from hepatocytes. "STIP1 may also serve as a potential biomarker for cholangiocellular carcinoma and hepatocellular carcinoma." (PMID 27409672, 2016). "STIP1 is thought to be involved in mediating the process of tumor proliferation, migration, and invasion, and it is capable of being secreted by a wide range of cancer cells (including hepatocellular carcinoma cells) and can act as a cytokine in order to regulate tumor progression." (PMID 38635528, 2024). "The positive correlations between STIP1 and JAK2 expression were also seen in other cancer types, including hepatocellular carcinoma and breast cancer." (PMID 27409672, 2016). "Heat shock protein 90 beta (HSP90β) promotes the progression of hepatocellular carcinoma (HCC) by suppressing STIP1 homology and U‐box‐containing protein 1 (STUB1)‐induced YTHDF2 ubiquitination, which may inaugurate a novel intervention strategy for the treatment of HCC." (PMID 37515378, 2023). "This study aimed to investigate the diagnostic value of stress-induced phosphoprotein 1 (STIP1) in serum for hepatocellular carcinoma (HCC) and alpha-fetoprotein (AFP)–negative HCC (ANHC)." (PMID 38780206, 2024).
breast carcinoma (6 papers, 2013 to 2022). "For example, a compound that prevents Hsp90 from interacting with STIP1 has been recently designed and shown to impair the Hsp90-dependent folding pathway, ultimately exerting cytotoxic effects on breast cancer cells." (PMID 23468915, 2013). "In addition, STIP1 and actin colocalized at the leading edges of pseudopodia in breast cancer cells and knockdown of STIP1 resulted in decreased levels of RhoC and a reduction in pseudopodia formation." (PMID 32365744, 2020). "For example, a compound that blocks HSP90 interaction with STIP1 impairs the HSP90-dependent folding pathway and is toxic to breast cancer cells." (PMID 28199984, 2017).